ARHGEF4 (Rho guanine nucleotide exchange factor 4)
Description:
Acts as a guanine nucleotide exchange factor (GEF) for RHOA, RAC1 and CDC42 GTPases. Binding of APC may activate RAC1 GEF activity. The APC-ARHGEF4 complex seems to be involved in cell migration as well as in E-cadherin-mediated cell-cell adhesion. Required for MMP9 up-regulation via the JNK signaling pathway in colorectal tumor cells. Involved in tumor angiogenesis and may play a role in intestinal adenoma formation and tumor progression.
Synonyms: Asef; Asef1; KIAA1112; STM6; GEF4
Tractability: Antibody: UniProt places it where antibodies can reach, with high confidence; its Gene Ontology location is reachable by antibodies, with medium confidence. PROTAC: ubiquitination databases record sites on it.
Gene: Protein-coding gene on chromosome 2 (130,836,914 to 131,047,263, forward strand). Ensembl gene ENSG00000136002.
Subcellular location: Cytoplasm (Isoform 3); Cell projection, ruffle membrane
Pathways (Reactome):
Signal Transduction: CDC42 GTPase cycle; G alpha (12/13) signalling events; NRAGE signals death through JNK; RAC1 GTPase cycle; RHOA GTPase cycle
Cell-Cell communication: SRC activates STAT3 in a quantitative manner, through Cadherin-11 (CDH11), RAC1 and gp130 (IL6ST)
Gene Ontology:
Molecular function: guanyl-nucleotide exchange factor activity; protein binding; protein domain specific binding
Biological process: filopodium assembly; lamellipodium assembly; regulation of small GTPase mediated signal transduction; intracellular signal transduction
Cellular component: cytosol; cytoplasm; ruffle membrane
Genetic constraint (gnomAD): Loss-of-function variants: 119 observed, 156.67 expected, observed/expected ratio (o/e) 0.76, 90% interval 0.65 to 0.88. The upper end of that interval is the gene's LOEUF score, 0.88, which puts it in group 3 of 6, group 1 being the genes least tolerant of losing a copy. Missense variants: 2,488 observed, 2,450.7 expected, observed/expected ratio (o/e) 1.02, 90% interval 0.98 to 1.05. Synonymous variants: 1,014 observed, 976.35 expected, observed/expected ratio (o/e) 1.04, 90% interval 0.99 to 1.09.
Homologues: Orthologues: chimpanzee ARHGEF4 (99% identical), macaque ARHGEF4 (90% identical).
Diseases named in the same sentence as ARHGEF4 in open-access papers:
ARHGEF4 is named in the same sentence as 16 diseases in open-access papers, as found by Europe PMC text mining. Sharing a sentence is not in itself a finding about the gene and the disease. The quoted sentences say what the papers report.
colorectal cancer (2 papers, 2021). A primary or metastatic malignant neoplasm that affects the colon or rectum. "Metastasis is the major cause of death in colorectal cancer and it has been proven that inhibiting an interaction between adenomatous polyposis coli (APC) and Rho guanine nucleotide exchange factor 4 (Asef) efficaciously restrain metastasis." (PMID 33670371, 2021). "In Colorectal cancer (CRC), adenomatous polyposis coli (APC) directly interacts with the Rho guanine nucleotide exchange factor 4 (Asef) and releases its GEF activity." (PMID 33968990, 2021).
pancreatic cancer (2 papers, 2019 to 2022). "We previously reported that overexpression of PODXL, BCL7B, and ARHGEF4 in pancreatic cancer tissue is correlated with pancreatic cancer-related survival." (PMID 31166991, 2019). "ARHGEF4 predicts poor prognosis and promotes cell invasion by influencing ERK1/2 and GSK-3/ signaling in pancreatic cancer." (PMID 36241648, 2022). "The aim of this study was to investigate the use of PODXL, BCL7B, ARHGEF4, and the integrin family member ITGB1 as useful markers for the prognosis of postoperative pancreatic cancer patients in comparison with tumor size and the tumor node metastasis (TNM) staging system." (PMID 31166991, 2019).
Abdominal obesity (1 paper, 2017). Excessive fat around the stomach and abdomen. "Our results indicate a possible contribution of CNVs in LEPR, NEGR1, ARHGEF4, and CPXCR1 and the intergenic regions 12q15c, 15q21.1a, and 22q11.21d to the development of obesity, particularly abdominal obesity in Mexican children." (PMID 28428959, 2017).
adenoma (1 paper, 2021). A neoplasm arising from the epithelium. "These authors found that OPLAH alone and/or a combination of a few methylated DNA markers (ARHGEF4, LRRC4, ANTXR1, PITX1) can discriminate adenomas and CRC in LS patients." (PMID 34201893, 2021).
autism (1 paper, 2021). Persistent deficits in social interaction and communication and interaction as well as a markedly restricted repertoire of activity and interest as well as repetitive patterns of behavior. "Even though the expression level of ARHGEF4 was not significantly down-regulated in autism samples, it was still expressed lower in autism samples compared with controls." (PMID 33716802, 2021).
epilepsies (1 paper, 2018). "Four patients with RE carried CNVs that disrupted genes known to cause other epilepsies; KCTD7, ARHGEF4, ARHGEF15 and CACNA2D1, expanding the phenotypes associated with these genes." (PMID 29789371, 2018). "Five patients with RE carried a rare CNV that disrupted genes associated with other epilepsies (KCTD7, ARHGEF15, CACNA2D1, GRIN2A and ARHGEF4), and 17 cases carried CNVs that disrupted genes associated with other neurological conditions or that are involved in neuronal signalling/development." (PMID 29789371, 2018).
Obesity (1 paper, 2017). Accumulation of substantial excess body fat. "The analysis of CNVs in six regions corresponded to five genes previously associated with obesity, LEPR (intron 2 and intron 3), NEGR1, ARHGEF4, CPXCR1, and INS, and four intergenic regions (1p36.33b, 12q15c, 15q21.1a, and 22q11.21d)." (PMID 28428959, 2017). "For ARHGEF4, we found that children with obesity more frequently showed gains (22.6%) as also observed for CPXCR1 (49.2%), whereas for INS losses occurred most frequently in obese children (25.7%)." (PMID 28428959, 2017). "The purpose of this study was to evaluate the association between CNVs in specific regions of LEPR, NEGR1, ARHGEF4, CPXCR1, and INS and in four intergenic regions (1p36.33b, 12q15c, 15q21.1a, and 22q11.21d) and obesity in Mexican children." (PMID 28428959, 2017). "In this study, we found significant differences in the copy numbers among children with obesity compared to those in normal weight children for LEPR, NEGR1 ARHGEF4, CPXCR1, and INS and four intergenic regions previously associated with obese children." (PMID 28428959, 2017).
preeclampsia (1 paper, 2025). Preeclampsia is a hypertensive disorder of pregnancy that is characterized by new-onset hypertension with proteinuria presenting after 20 weeks of gestation, and depending on mild or severe forms may initially present with severe headache, visual disturbances, and hyperreflexia. "LEP and ARHGEF4, involved in metabolic and hypoxia/angiogenesis pathways, are shown to be upregulated (in accordance with our result) in placentas from severe preeclampsia (sPE) patients across ancestries, suggesting its contribution to the pathophysiology of preeclampsia." (PMID 40357364, 2025).
cancer (8 papers, 2013 to 2025). A tumor composed of atypical neoplastic, often pleomorphic cells that invade other tissues. "A panel of five DNA methylation markers (FER1L4, ZNF671, ST8SIA1, TBX15, and ARHGEF4) detected 74% of EC cancer patients with an overall specificity of 91%." (PMID 35242243, 2022). "Interestingly, many of the DMGs identified had multiple roles and several were potential cancer biomarkers or were previously shown to be implicated in various types of cancers, including ABLIM1, ADAM12, ARHGEF4, FBLN2, ITGA6, LRPAP1, Ly9, NT5E, PITPNC1, PLCG1, OBSCN, RHOH, SPTBN1, SPOCK2 and SPRY1." (PMID 41159936, 2025). "Among the 135 samples, TFAP2B, ARHGEF4, and RAPGEFL1 had the highest values in 60, 37, and 38 samples, respectively, and the highest values were defined as the fractions of cancer cells in the samples." (PMID 24312652, 2013). "However, TFAP2B in sample Et5T, ARHGEF4 in Et1T, Et2T, Et4T, and Et5T, and RAPGEFL1 in Et2T were not completely methylated, possibly due to heterogeneity among cancer cells." (PMID 24312652, 2013).
tumor (8 papers, 2013 to 2024). "We investigated the abilities of PODXL, BCL7B, ARHGEF4, and ITGB1 to predict prognosis in PDAC in comparison with UICC TNM stage and tumor size." (PMID 31166991, 2019). "In the present study, we investigated the use of PODXL, BCL7B, ARHGEF4, and ITGB1 as useful markers for the prognosis of postoperative PDAC patients in comparison with tumor size and the TNM staging system." (PMID 31166991, 2019). "Specific IGF2BP3-bound transcripts—ARF6 and ARHGEF4—that are preferentially translated in membrane protrusions induce further formation of membrane protrusions; consequently, IGF2BP3 promotes cell invasiveness and tumor metastasis." (PMID 25216519, 2014). "Furthermore, fibroblast growth factor receptor 2 (FGFR2); ARHGEF4, which acts as a guanine nucleotide exchange factor; and SDC1, a member of the syndecan proteoglycan family, were also expressed at significantly lower levels in ulcerated tumours." (PMID 23383013, 2013). "PODXL, BCL7B, ARHGEF4, ITGB1, or tumor size were not included in the final model of the multivariate analysis." (PMID 31166991, 2019).
ARHGEF4 also shares sentences with these, for which no sentence is quoted: autism spectrum disorder (1 paper); bladder cancer (1); breast carcinoma (1); breast tumors (1); colon cancer (1); colorectal tumor (1).